CD36 (CD36 molecule (CD36 blood group))
Diseases named in the same sentence as CD36 in open-access papers (continued):
Sharing a sentence is not in itself a finding about the gene and the disease.
lymph node metastasis (11 papers, 2019 to 2023). "The study also demonstrated a 45-fold increased risk of lymph node metastasis in the CD36-high group." (PMID 36568966, 2022). "Our data showed that CD36 is strongly associated with the occurrence of lymph node metastasis and has a stronger association with positive N-status than grading." (PMID 34439279, 2021). "We performed a histopathological examination of CD36 expression in OSCC to investigate it as a potential individual risk factor for the occurrence of lymph node metastasis." (PMID 34439279, 2021). "Potentially, the association of CD36 and lymph node metastasis is stronger in our sample of severe cancer cases compared to all head and neck cancer patients." (PMID 34439279, 2021). "This carries the risk that the observed relationship between CD36 and N stage is expression of an unobserved cofounder causing both high CD36 level and lymph node metastasis." (PMID 34439279, 2021). "In our study, overexpression of CD36 increases the risk of lymph node metastasis by 45-fold." (PMID 34439279, 2021). "In addition, higher CD36 expression was associated with lymph node metastasis (p < 0.05) and poor prognosis (p = 0.030) in 79 Chinese GC patients." (PMID 33232276, 2020). "CD36 may be useful for risk stratification regarding lymph node metastasis in OSCC." (PMID 34439279, 2021). "CD36 could be used in the future for risk stratification concerning lymph node metastasis and might guide surgeons in the decision-making process of the necessity of cervical lymph node dissection, especially if there is uncertainty whether a cervical lymph node dissection is indicated." (PMID 34439279, 2021). "By inhibiting CD36, the occurrence of lymph node metastasis can be blocked, and the presence of CD36 positive cells is associated with the recurrence of metastasis of malignant tumors in different systems, suggesting that CD36 may play an important role in the recurrence of tumor metastasis." (PMID 31660264, 2019). "Although cells with a mutant CD36 (CD36-K164A) can generate some lymph node metastasis, the lesions have cells with increased content of LD, indicating that CD36 is essential for the metabolic reprogramming coupled to the adapting to the metastatic niche." (PMID 36568966, 2022). "Last, in this study, we observed that miR-27a-3p levels negatively correlated with CD36 mRNA levels in tumoral tissues in the group of patients reporting lymph node metastasis." (PMID 36556492, 2022). "The logistic regression with binary N status as a dependent variable showed that high CD36 expression increased the chance for lymph node metastasis 45-fold (OR = 44.7, 95% CI: 10.0–316)." (PMID 34439279, 2021). "In this regard, a prospective study is necessary to investigate a possible relationship between FA uptake, CD36, and the occurrence of lymph node metastasis." (PMID 34439279, 2021). "Within the N+ group, the progression-free survival differed between high and low CD36 expression, but there are only few cases with low CD36 expression and lymph node metastasis." (PMID 34439279, 2021). "T1 und T2 tumors with a high CD36 also showed a strong correlation with the existence of lymph node metastasis." (PMID 34439279, 2021). "Only eight patients with low CD36 expression suffered from lymph node metastasis compared to 32 with high CD36 expression." (PMID 34439279, 2021). "This study showed a clear correlation between CD36 expression and the occurrence of lymph node metastasis." (PMID 34439279, 2021). "In terms of sensitivity and specificity, CD36 showed a promising sensitivity (80%) and specificity (86%) in univariate prediction of lymph node metastasis." (PMID 34439279, 2021). "This meant that by preoperative biopsy and histopathological examination of CD36, we could distinguish patients with lymph node metastasis, although their 18FDG-PET/CT showed N0 results." (PMID 37207149, 2023).
lymph node metastasis (continued). "However, the lack of an in vitro assay proving the direct or indirect correlation between the presence of lymph node metastasis, CD36, and miR-27a-3p expression levels represents a limitation of this study." (PMID 36556492, 2022). "Accordingly, the very high OR and CI estimates for high CD36 and lymph node metastasis might indicate an overfitting of multiple regression models." (PMID 34439279, 2021). "In summary, CD36 is useful as a specific parameter for lymph node metastasis." (PMID 34439279, 2021). "Of 40 patients suffering from lymph node metastasis, 32 (80%) had high CD36 expression." (PMID 34439279, 2021). "CD36 may be useful as a specific parameter for lymph node metastasis and as a progression parameter for survival." (PMID 34439279, 2021). "Summarizing our results shows that lymph node metastasis, high grading and increased T-status occurred much more frequently in the high CD36 group than for low CD36 status, an indication that CD36 could be associated with a more aggressive disease course." (PMID 34439279, 2021). "Additionally, this study does not consider tumor markers such as CD36, which are associated with increased incidence of lymph node metastases." (PMID 36077775, 2022). "The hypothesis was that CD36 expression correlates with the occurrence of lymph node metastasis." (PMID 34439279, 2021). "Therefore, CD36 could be useful for risk stratification regarding lymph node metastasis in OSCC and, beyond that, CD36 could also be a possible therapeutic target in future." (PMID 34439279, 2021). "We observed that the level of CD36 in GC tissues was significantly associated with age, Lauren type, pStage, depth of invasion and number of positive lymph nodes but was not related to gender, distant metastasis or lymph node metastasis." (PMID 31410220, 2019). "CD36 is expressed in OSCC and correlates with tumor grading, T-status, and especially the occurrence of lymph node metastasis." (PMID 34439279, 2021). "Furthermore, it is unknown whether CD36 expression is a suitable marker for lymph node metastasis." (PMID 34439279, 2021). "On the opposite, FACS-sorted CD36− do not generate lymph node metastasis and CD36 expression knock-down by short-harpin RNA (shRNA) reduces the metastatic burden." (PMID 36568966, 2022). "The positive predictive value of high CD36 status for lymph node metastasis was 84% and the negative predictive value of low CD36 for N0 status was 82%." (PMID 34439279, 2021). "Interestingly, CD36 and miR-27a-3p were downregulated and upregulated, respectively, in tumoral tissues compared to peritumoral and control tissues, with a significant negative correlation in the group of patients developing lymph node metastasis." (PMID 36556492, 2022).
lymphoma (11 papers, 2017 to 2025). A malignant (clonal) proliferation of B- lymphocytes or T- lymphocytes which involves the lymph nodes, bone marrow and/or extranodal sites. "The study assessed PD-L1/PD-1 expression in circulating CXCR3 and CD36-positive lymphocytes in lymphoma." (PMID 36726488, 2023). "The results also assume that posttherapy PDL1+CD36+% and PD-1+CD36+ percentages are correlated with poor prognosis, considering prognostic biomarkers in lymphoma patients." (PMID 36726488, 2023). "Other studies found that individuals with various forms of lymphoma had a higher percentage of peripheral CD36 and CXCR3+ lymphocytes, implying that lymphoma patients have an immunological defect." (PMID 36726488, 2023). "High pretherapy CXCR3+% and CD36+% of cells were observed in lymphoma patients than in normal volunteers (median: 40% vs. 11.2%; 13% vs. 4.2%, P < 0.001)." (PMID 36726488, 2023). "The coexpression of PD-L1/PD-1 with CXCR3/CD36 on circulating lymphocytes was analyzed by flow cytometry in 78 lymphoma patients before and after therapy and in 50 healthy controls." (PMID 36726488, 2023). "Low PD-L1/PD-1+CD36 percentages promote peripheral cell proliferation, providing a possible antitumor mechanism in lymphoma." (PMID 36726488, 2023). "PD-L1/PD-1 coexpression with CXCR3/CD36 in peripheral lymphocytes in lymphoma still needs to be clarified." (PMID 36726488, 2023). "The current study investigated PD-L1/PD-1 coexpression with CXCR3/CD36 in circulating lymphocytes, serum IL-19 levels, and their correlation with clinical outcome and extranodal involvement in lymphoma." (PMID 36726488, 2023). "In this study, the percentage of peripheral CXCR3 and CD36 positive lymphocytes differed significantly between lymphoma patients and healthy controls." (PMID 36726488, 2023). "The findings presuppose that CXCR3/CD36 and PDL1/PD-1 coexpression have a crucial role in lymphoma development, suggesting using this coexpression as a diagnostic test in managing lymphoma." (PMID 36726488, 2023). "High percentages of circulating PD+L1+CD36+ and PD-1+CD36+ lymphocytes were found in lymphoma subjects with extranodal involvement." (PMID 36726488, 2023). "Coculture of M(IFN-γ/LPS) macrophages with apoptotic lymphoma cells significantly increased the expression of Mrc1, Timp2, Cd36, Pparg and Gas6, whereas the expression of Tnf and Il6 were significantly decreased." (PMID 28157210, 2017). "Thus, according to the findings, PD-L1/PD-1+CD36+% is insufficient for identifying extranodal involvement in lymphoma patients." (PMID 36726488, 2023). "Lymphoma progression and extranodal involvement in lymphomas could be initiated by PD-L1/PD-1 coexpression with CD36." (PMID 36726488, 2023). "Interestingly, FcγRIV+/CD36+ macrophages in cyclophosphamide-treated lymphoma model mice also showed a “super-phagocytic” capacity." (PMID 37174614, 2023). "In conclusion, PD-L1/PD-1 coexpression with CXCR3/CD36 and serum IL-19 may be involved in lymphoma extranodal involvement and have prognostic and predictive values in lymphoma." (PMID 36726488, 2023). "Coexpression of PD-L1/PD-1 with CXCR3/CD36 in circulating lymphocytes and serum IL-19 levels contributes to poor prognosis and might be potential markers for extranodal involvement in lymphoma." (PMID 36726488, 2023). "The findings could also shed light on the role of circulating CXCR3 and CD36-positive lymphocyte cells in lymphoma." (PMID 36726488, 2023). "PD-L1/PD-1 coexpression with CXCR3/CD36 and IL-19 might play an inferior prognostic role in lymphoma, providing a new significant era in lymphoma immunotherapy, especially in patients with extranodal involvement." (PMID 36726488, 2023). "Interestingly, PD-L1+CD36+% and PD-1+CD36+% in newly diagnosed lymphoma subjects were significantly higher than in healthy volunteers (median: 8% vs. 1%; 5 vs. 0.2, P < 0.001)." (PMID 36726488, 2023).
lymphoma (continued). "In addition to CD68 and CD163, S100A9, CCR2, CD32, CD36, and Slan were also critical in the characterization of lymphoma‐specific tumor macrophages." (PMID 33135337, 2020). "PD-L1/PD-1 coexpression with CXCR3/CD36 could significantly impact clinical lymphoma activity." (PMID 36726488, 2023). "Immunohistochemistry (IHC) staining of CD36 from HPA database revealed significant expression in various tumorous tissues, including breast, liver, cervical, and lymphoma." (PMID 41550652, 2025). "Flow cytometric analysis investigated CD36 and CXCR3 expression in peripheral lymphocytes in 78 newly diagnosed lymphoma patients and 50 healthy controls." (PMID 36726488, 2023). "PD-L1/PD-1 coexpression with CXCR3/CD36 in circulating lymphocytes was investigated in posttherapy lymphoma patients with extranodal involvement (n = 34) or without extranodal involvement (n = 44)." (PMID 36726488, 2023). "In our cohort of patients, the expression of CD36 was significantly elevated in CD5+ non-DE lymphoma than its CD5− counterpart, consistent with the previous findings that CD36 is one of the top variant genes that distinguished CD5+ from CD5− DLBCL." (PMID 36276140, 2022). "PD-L1/PD-1 coexpression with CXCR3/CD36 in peripheral lymphocytes has not been studied in lymphoma." (PMID 36726488, 2023). "However, lymphoma patients without extranodal involvement had a lower posttherapy PDL-1/PD-1 coexpression with CXCR3/CD36 than in the pretherapy samples of the same patients." (PMID 36726488, 2023). "In lymphoma patients without extranodal involvement, posttherapy PD-L1/PD-1 and CXCR3/CD36 coexpression were reduced, suggesting that chemotherapy might induce a disruption in PD-1/PD-L1 signaling." (PMID 36726488, 2023). "The upregulation of Gas6, Mrc1, Cd36 and Timp2 expression by M(IFN-γ/LPS) macrophages was specific for coculture with apoptotic cells, as coculture with unstimulated or Bcl-2-transfected lymphoma cells did not lead to a significant upregulation of these genes." (PMID 28157210, 2017). "The addition of metformin significantly decreased the M2 proportion and the CD36 expression level in the coculture systems, indicating that metformin could target altered lipid metabolism and decrease M2 macrophages in DLBCL, especially in CD5+ non-DE lymphoma." (PMID 36276140, 2022).
asthma (10 papers, 2019 to 2026). "The scavenger receptor CD36, known to have a function in bacterial recognition, and potentially implicated in asthma exacerbations in response to bacterial infections, was higher expressed by BALF exosomes from asthmatics, compared to healthy controls." (PMID 38957448, 2024). "The observation of a putative causal relationship between genetic variations in CD36, basophil activation and childhood asthma risk and severity may point to a new intervention point for targeted asthma therapies." (PMID 36653562, 2023). "This study, focusing on the OVA-induced type 2-high asthma subtype, demonstrates for the first time a significant downregulation of CD36 surface expression on AMs in this model." (PMID 41181101, 2025). "Collectively, CD36 is a critical mediator through which ADAM17 regulates the phagocytic function of AMs in the OVA-induced asthma model." (PMID 41181101, 2025). "Asthmatics BALF exosomes showed higher levels of tetraspanins CD81 and CD63, of HLA-DR, and CD36, a scavenger receptor with a potential role in asthma exacerbations in response to bacterial infections, compared to healthy controls." (PMID 38957448, 2024). "CD36+ EVs accelerate disease progression by activating inflammation through the heterodimerization of TLR4/6 in asthma." (PMID 36959535, 2023). "The transfer of CD36+ exosomes would favor asthma progression by promoting inflammation through TLR4 and TLR6 complex formation." (PMID 30759880, 2019). "Though, the role of S100A family proteins in TLR and CD36 signaling in the context of severe asthma remains unclear and needs further investigation." (PMID 37996952, 2023). "By focusing on the type 2-high asthma subtype, elucidating the distinct regulatory mechanism of CD36, and establishing a comprehensive in vitro and in vivo validation framework, this study provides systematic evidence for targeting phagocytosis-related mechanisms in asthma therapy." (PMID 41181101, 2025). "Our findings showed that ADAM17, a key downstream effector molecule of TNF-α, impaired AMs phagocytic function by downregulating the expression of the phagocytic receptor CD36, thereby contributing to the pathogenesis of OVA-induced asthma model." (PMID 41181101, 2025). "In asthma, the expression levels of CD81, CD36 and HLA-DR in airway exosomes are increased." (PMID 30759880, 2019).
Cerebral ischemia (10 papers, 2012 to 2025). Restriction of arterial blood supply to the brain associated with insufficient oxygenation to support the metabolic requirements of the tissue. "CD36-deficient mice display significantly reduced TLR2/1-mediated inflammation following cerebral ischemia, suggesting that CD36 is crucial for TLR2/1 signaling in AD and may contribute to sterile inflammation." (PMID 40429737, 2025). "In animal models of cerebral ischemia, PPARγ activation by rosiglitazone also increases CD36 expression in microglia, which contributes to the resolution of inflammation and clearance of infiltrated neutrophils at 48 h following cerebral ischemia." (PMID 37601043, 2023). "CD36 appears to be involved in pathologies such as brain ischemia, where CD36 expression is increased mostly in cells expressing the microglia/macrophage marker CD11b." (PMID 23737655, 2013). "Moreover, lack of Cd36 exacerbated injury in cerebral ischemia models associated with reduced engulfment of apoptotic neurons and enhanced Nf-κB signaling." (PMID 29494550, 2018). "In contrast to the beneficial role of CD36 in ICH models, genetic deletion studies have shown that CD36 aggravates acute brain injury at 3 days after cerebral ischemia." (PMID 37601043, 2023). "However, CD36 may play a differential role in the recovery phase following cerebral ischemia." (PMID 37601043, 2023).